FGF21 (fibroblast growth factor 21)
Diseases named in the same sentence as FGF21 in open-access papers (continued):
Sharing a sentence is not in itself a finding about the gene and the disease.
Obesity (continued). "FGF21 has been reported to normalize glucose and lipid homeostasis, thus preventing the development of metabolic disorders, such as obesity and diabetes." (PMID 35557960, 2022). "FGF21 mimetics and analogues have advanced to clinical trials in patients with T2D, obesity and non-alcoholic steatohepatitis." (PMID 35563026, 2022). "Accordingly, pharmacological recombinant fibroblast growth factor 21 therapies have been shown to counteract obesity and its related metabolic disorders in both rodents and nonhuman primates." (PMID 36362103, 2022). "When patients with obesity and type 2 diabetes mellitus lose body weight, FGF21 levels also decrease." (PMID 35572519, 2022). "Consistently, pharmacological recombinant FGF21 therapies have been shown to counteract obesity and its related metabolic disorders in both rodents and nonhuman primates." (PMID 36362103, 2022). "In conclusion, we confirmed serum FGF-19 and FGF-21 as useful new markers of obesity-related metabolic alternations and we robustly propose Rb as a novel indicator of excessive body adiposity and its early consequences." (PMID 36362225, 2022). "On the other hand, previous studies have shown that circulating levels of FGF-21 are increased in pathologies such as obesity, metabolic syndrome, insulin resistance, cardiovascular disease and different chronic inflammatory processes." (PMID 35883694, 2022). "Endogenous FGF21 serum levels, however, are increased during obesity-related diseases, suggesting the development of FGF21 resistance during obesity and the successive lowering of FGF21 efficacy." (PMID 36289764, 2022). "Intriguingly, it has been demonstrated that hepatic mitochondrial respiration is activated in patients with obesity-related fatty liver who have elevated serum FGF21 concentrations." (PMID 35663311, 2022). "In response to exercise, FGF-21 is released from muscle into the bloodstream and prevents some diseases, especially sarcopenia and obesity." (PMID 35250869, 2022). "Abnormal increase in FGF21 levels has been consider as a signal of endothelial cell injury as reported in the diseases including obesity, dyslipidemia, metabolic syndrome, hypertension, CAD, DM, and nonalcoholic fatty liver." (PMID 36213282, 2022). "FGF21 administration ameliorated age-related metabolic disorders including insulin resistance, dyslipidemia, and obesity in rodents." (PMID 35012677, 2022). "The obesity resistance is dependent on FGF21, as UCP1/FGF21 dKO mice gain similar body weight and fat mass as WT and FGF21 KO control mice." (PMID 36034414, 2022). "Biological effects of a variant of FGF21, LY2405319, were tested in patients with obesity and diabetes." (PMID 35012677, 2022). "Still, the majority of the recent studies support a concept that FGF21 action and sensitivity are required in adipose tissue for metabolic improvements during obesity and insulin resistance." (PMID 36034414, 2022). "Endogenous FGF21 fully mediates obesity resistance in mice with genetic inactivation of the adipose-specific mitochondrial uncoupling protein 1 (UCP1), when fed high fat diets (HFD) at room temperature (representing mild cold conditions)." (PMID 36034414, 2022). "Regarding the circulating markers of BAT activity, CXCL14, secretin, and 12,13-dihydroxy-9Z-octadecenoic acid (12,13 di-HOME) were similar in the two groups, whereas there was a trend for higher FGF21 in the subjects overweight/obesity." (PMID 35928901, 2022). "An FGF-21-resistance state can be reversed by weight loss or hypoglycemic therapy and FGF-21 transgenic mice or administration of exogenous FGF-21 resulted in resistance to diet-induced obesity, pointing at FGF-21 as a potential anti-obesity molecule." (PMID 36362225, 2022). "Paradoxically, both the circulating and tissue (e.g., liver, skeletal muscle, and AT) levels of FGF21 are elevated under nutrient-excess states such as obesity, suggesting the presence of FGF21 resistance or an adaptive response in obesity." (PMID 35909571, 2022).
Obesity (continued). "Studies have shown increased FGF21 in obesity and NAFLD, whereas pharmacological administration of FGF21 is beneficial to body weight loss, alleviation of fatty liver, dyslipidemia and hyperglycemia." (PMID 35347118, 2022). "In uncoupling protein 1 knockout (UCP1 KO) mice, however, elevated endogenous FGF21 levels mediate resistance against diet-induced obesity." (PMID 36034414, 2022). "In line with our findings in the CDAHFD mouse model, previous studies showed that FGF21 successfully amended obesity and diabetes in a high-fat diet (HFD) model." (PMID 35743140, 2022). "A hormone produced mainly by the liver called fibroblast growth factor 21 (FGF21) is closely linked to the energy status and is increased in patients suffering from obesity or insulin resistance." (PMID 35282437, 2022). "Obesity in humans and mice is associated with elevated levels of two hormones responsive to cellular stress, namely GDF15 and FGF21." (PMID 36064109, 2022). "Importantly, these observations started discussions whether obesity may cause FGF21 resistance." (PMID 36034414, 2022). "Previous studies have shown that mice fed a high-fat diet, and patients and animals with obesity or diabetes have higher levels of endogenous FGF21, but its physiological function is considerably lower than that of exogenous recombinant FGF21." (PMID 36006939, 2022). "More importantly, previous studies indicate that injecting intraperitoneally FGF21 into mice can significantly attenuate neurodegeneration in mice with diabetes and obesity through metabolic modulation and anti-proinflammatory effects." (PMID 35002679, 2021). "This can be explained based on the action of this factor on the uptake of glucose in adipose tissue in the case of obesity or overweight, the elevation of FGF21 can be seen as a consequence." (PMID 34019585, 2021). "Studies have demonstrated impaired FGF21 signaling in the liver, pancreas, and white adipose tissue of obese mice, initially suggesting that obesity is an FGF21-resistant state." (PMID 33762965, 2021). "If the primary effect of FGF21 is an increase in body temperature setpoint rather than an increase in energy expenditure, the translational perspectives of FGF21 treatment as an anti-obesity strategy would be less promising." (PMID 34418595, 2021). "Since FGF21 is expected as a new therapy for obesity and obesity-related diseases, effective conditions are needed to be evaluated." (PMID 34799626, 2021). "In female mice with diet-induced obesity, as well as in male mice, FGF21 administration beneficially affected glucose and lipid metabolism and taste preferences, despite significant sex differences in adiposity rates and metabolic characteristics." (PMID 34638898, 2021). "Nonetheless, FGF21 was dispensable for the resistance to diet-induced obesity (DIO) and IR observed in these mice, which were mediated by alternative mechanisms downstream of ATF4." (PMID 33944779, 2021). "There is mounting evidence indicating that the elevated FGF21 expression from skeletal muscle under a variety of stresses can regulate whole-body metabolism as evidenced by preventing diet-induced obesity and insulin resistance." (PMID 33762965, 2021). "Endurance exercise with dietary interventions has been reported to significantly reduce the levels of circulating FGF21 in elderly patients with obesity." (PMID 33498410, 2021). "Nutrient overload and obesity are also capable of influencing gene expression and circulating levels of FGF21 in mice and humans." (PMID 33762965, 2021). "Irisin and Fibroblast Growth Factor 21 (FGF-21) have been proposed as prognostic and/or diagnostic biomarkers in subjects with obesity and metabolic syndrome, because they increase earlier than other traditional biomarkers." (PMID 33924457, 2021).
Obesity (continued). "Recombinant human FGF21 administration effectively improved obesity-induced cognitive dysfunction and anxiety-like behavior, and this suggested that FGF21 had a beneficial regulation on the central nervous system." (PMID 34800969, 2021). "Circulating FGF21 levels are elevated in diabetic and obese subjects and administration of FGF21 has been shown to enhance insulin sensitivity and reverses obesity by increasing energy expenditure." (PMID 34680216, 2021). "In the last decade, FGF21 has emerged as an appealing therapeutic for obesity and the metabolic syndrome with pleiotropic effects on thermogenesis, fatty acid oxidation, glucose metabolism, and body weight." (PMID 33411693, 2021). "In accordance with these findings, 12 weeks of FGF21 administration reduced body weight and TG levels and improved glucose tolerance, while two weeks of FGF21 treatment significantly reduced liver dysfunction in monkeys with HFD-induced obesity." (PMID 33498410, 2021). "It is well-documented that the protective effect of exogenous FGF21 on obesity and T2DM is closely depends on the activation of SIRT1 and subsequently leads to the deacetylation of its downstream targets, PGC-1α and H3 in human adipocytes." (PMID 34349728, 2021). "Our data support a link between FGF21 and sweet preference in humans, including people with severe obesity." (PMID 34836096, 2021). "In humans, high levels of serum FGF21 have been found in people with obesity, particularly when metabolic complications are present such as type 2 diabetes." (PMID 34019585, 2021). "The recent discovery of FGF21 as an anti-obesity and anti-inflammation factor and as a downstream target of KRAS has shed new light on the problem." (PMID 33668583, 2021). "The serum levels of FGF21 are increased in the settings of hyperlipidemia, obesity, diabetes, and fatty liver." (PMID 33668583, 2021). "Studies conducted in a UCP1/FGF21 double knockout (dKO) model have demonstrated a full reversal of obesity resistance in dKO mice by inhibiting the metabolic reprogramming of WAT genes responsible for enhanced lipid and oxidative metabolism." (PMID 34185433, 2021). "Values of seral FGF-21 have been positively correlated to several CVD-related risk factors, such as DM, obesity, metabolic syndrome, hypertension, and even brachial-ankle PWV." (PMID 33810243, 2021). "The aim of this study was to compare the effects of FGF21 on food preferences and glucose and lipid metabolism in C57Bl/6J male and female mice with diet-induced obesity." (PMID 34638898, 2021). "Beneficial effects of exogenous FGF21 on insulin sensitivity have so far been reported only from animals experiencing excessive nutrition and obesity." (PMID 34517929, 2021). "A consensus in past studies supports that PPARα controls hormones that regulate adiposity, especially in the liver, such as PPARα-induced fibroblast growth factor 21 (FGF21), a well-established anti-obesity and anti-diabetic hepatokine hormone." (PMID 35011564, 2021). "As a result, a blood epigenetic profile characteristic for high serum FGF21 in obesity was established." (PMID 33670024, 2021). "It is necessary to research the effect of FGF21 on hepatic steatosis in females with other forms of obesity." (PMID 34943946, 2021). "FGF21 has potent beneficial effects on obesity and diabetes which have been observed in rodents, monkeys, and humans." (PMID 34638898, 2021). "The current understanding is that the liver is the primary contributory organ of circulating FGF21in the setting of metabolically unhealthy obesity with unelucidated impact of FGF21 as a myokine to the systemic milieu." (PMID 33762965, 2021). "Transgenic mice overexpressing FGF21 exhibit resistance to the development of high fat diet (HFD)-induced obesity." (PMID 34046014, 2021). "One consequence of obesity is FGF21 resistance, which is described by high circulating FGF21 concentrations and greatly increased body weight." (PMID 34578793, 2021).
Obesity (continued). "In mice with diet-induced obesity, a single dose of recombinant Fgf21 is sufficient to improve insulin sensitivity and glucose disposal, and chronic administration promotes body weight loss and reduced adiposity." (PMID 34023388, 2021). "Increased Fgf21 during diet induced obesity in WT mice was accompanied by lower adiponectin production from white adipose tissue, possibly due to downregulation of the Fgf21 coreceptor βKlotho." (PMID 34603036, 2021). "It was documented that FGF21 becomes elevated as obesity develops, and positive correlations between BMI and FGF21 were observed." (PMID 34574358, 2021). "Mice that were deficient in KLB specifically from adipocytes were refractory to the effects of recombinant FGF21 to increase subcutaneous fat mass, suggesting that direct FGF21 signaling to adipocytes is required for subcutaneous fat expansion in obesity." (PMID 35046901, 2021). "FGF21 can protect animals from diet-induced obesity and reduce hepatic lipid accumulation, enhance glucose metabolism, and thus prevent hepatic steatosis, fibrosis, and NAFLD when administered to diabetic rodents." (PMID 33785868, 2021). "To explore the potential of utilizing in vivo FGF21 gene therapy for the treatment of obesity, we subjected C57BL6/J mice to a very-high-fat diet for 10 weeks and then transfected the mice with either pLIVE-Empty control vector or pLIVE-FGF21-HA." (PMID 34074713, 2021). "Regarding FGF-21, serum levels are typically elevated in patients with obesity and thus it was an exclusion criterion." (PMID 34572118, 2021). "FGF21 protein from subcutaneous and visceral WAT has been shown to be higher in obese db/db mice compared with lean littermates, suggesting an important role for Ad-FGF21 in genetic obesity models in addition to the better characterized Hep-FGF21." (PMID 35046901, 2021). "Fibroblast growth factor 21 (FGF21) plays a key role in dietary regulation, but FGF21 resistance is prevalent in obesity." (PMID 34578793, 2021). "Participants with obesity had ~6-fold higher serum FGF21 levels than lean controls at baseline, an effect that was equivalent in men and women." (PMID 35046901, 2021). "Given the remarkable success FGF21 has demonstrated in treating obesity in animals, researchers are actively investigating FGF21 for its potential use in a clinical setting." (PMID 34074713, 2021). "A growing body of literature has demonstrated that nutritional stressors and dietary macronutrient composition resulting in metabolically unhealthy obesity can regulate FGF21 expression and signaling, serving to coordinate and restore metabolic homeostasis." (PMID 33762965, 2021). "Although therapeutic administrating of FGF21 prevents diet-induced obesity and related insulin resistance in mice and humans." (PMID 33670024, 2021). "There is evidence that obesity is a state of FGF-21 resistance, both at the signaling and transcriptional level, that is characterized by an increase in FGF-21, but without the biological effects of this hepatokine." (PMID 34822430, 2021). "As previously suggested by Hui and cols., both adiponectin and FGF21 are considered promising therapeutic strategies in the prevention and treatment of obesity and related comorbidities." (PMID 34762789, 2021). "PPARα agonists, such as bezafibrate and a novel drug MHY2013, can significantly increase the expression of FGF21 for alleviating obesity-induced insulin resistance, dyslipidemia and hepatic steatosis." (PMID 34675822, 2021). "In this study, we evaluated the effect of FGF21 on the metabolism and taste preferences of both male and female mice with diet-induced obesity." (PMID 34638898, 2021). "Hepatic expression and circulating concentrations of Fgf21 are increased in mice and humans during the onset of obesity and NAFLD, suggesting a protective mechanism that is ultimately overwhelmed by sustained overnutrition." (PMID 34023388, 2021).
Obesity (continued). "Future studies are necessary to investigate the mechanisms involved in the action of FGF21 in obesity, and the possible interaction with inflammatory processes and energy homeostasis." (PMID 34762789, 2021). "In summary, our data present a novel methodology for the controlled delivery of hepatic FGF21 expression in mice and demonstrate the successful implementation of this strategy to reduce the effects of diet-induced obesity in female C57BL6/J mice." (PMID 34074713, 2021). "FGF21 is an important hepatokine whose expression positively correlates with therapeutic outcomes across various animal models of obesity." (PMID 34074713, 2021). "For FGF21, serum levels were slightly higher in the overweight/obesity groups in both patients and controls." (PMID 34019585, 2021). "Previous study has indicated that serum FGF21 level was increased in population with obesity or diabetes." (PMID 34011291, 2021). "Increased plasma concentrations of adiponectin have been consistently observed in non-human primates and humans with metabolic diseases (T2DM, obesity, non-alcoholic steatohepatitis) following treatment with various FGF21 analogs." (PMID 34517929, 2021). "The ability of FGF21 to improve glucose and lipid metabolism in animal models of genetic obesity opens up prospects for its use for the correction of comorbidities associated with genetic forms of obesity in humans." (PMID 34943946, 2021). "A new type of long-acting FGF21 (LAPS-FGF21) has been developed for potential therapeutic effects on obesity." (PMID 34675822, 2021). "To date, these FGF21 analogues have shown substantial improvement in dyslipidemia, while exerting a marginal effect on glycemic control in patients with obesity and type 2 diabetes." (PMID 34944728, 2021). "Potential application of FGF21 as an anti-obesity molecule has even been approved in a study, in which exogenous FGF21 was administered." (PMID 33869312, 2021). "Nevertheless, FGF21 is known to be elevated in patients with T2D, obesity and with MS, mostly having a higher BMI." (PMID 33805553, 2021). "The new long-acting FGF21 analog PF-05231023 is a promising potential drug for the treatment of type 2 diabetes, obesity and obesity-related diseases." (PMID 34675822, 2021). "Overall, our findings are of relevance in consideration of the use of FGF21 in the treatment of human obesity." (PMID 34418595, 2021). "Fibroblast growth factor 21 (FGF21) beneficially affects taste preferences and obesity, but its action has mainly been studied in males." (PMID 34638898, 2021). "Recently, the discovery of fibroblast growth factor 21 (FGF21) as a novel anti-obesity and anti-inflammatory factor and as a downstream target of mutant KRAS has shed new light on this problem." (PMID 33668583, 2021). "Our data corroborate both the efficacy of FGF21-based therapies in mouse models of obesity and the mechanisms through which these therapeutic effects occur." (PMID 34074713, 2021). "The dietary intake of soybean βCG reduces serum TG levels and visceral fat in hyperlipidemic humans and exerts anti-obesity effects by promoting postprandial circulating levels of fibroblast growth factor 21 (FGF21) in mice." (PMID 34445273, 2021). "Sex-based differences in the expression of FGF21 in the liver and other tissues have been found, which exhibited differential manifestation with respect to obesity and starvation." (PMID 34638898, 2021). "Fibroblast growth factor 21 (FGF21), a main regulator for obesity, reduces obesity-mediated inflammation." (PMID 34281285, 2021). "Due to the interest in FGF21 as an anti-obesity substance, we also examined the effect of FGF21 on body temperature control in mice that had been HFD-fed (at thermoneutrality) and were thus obese (≈50 g versus chow-fed ≈30 g body weight)." (PMID 34418595, 2021). "Circulating FGF21 levels are increased in obesity and diabetes accompanied by disturbed expression of its receptor levels, which points to a resistance state." (PMID 34321008, 2021).